IGF1 (insulin like growth factor 1)
Diseases named in the same sentence as IGF1 in open-access papers (continued):
Sharing a sentence is not in itself a finding about the gene and the disease.
hypopituitarism (continued). "Low insulin-like growth factor 1 (IGF-1) concentration is usually the first sign of hypopituitarism, but a normal IGF-1 level alone cannot exclude the presence of other hormonal abnormalities." (PMID 34030739, 2021). "Age, sex, IGF-1 concentrations, comorbidities, treatment modalities and pituitary insufficiency were documented." (PMID 30065700, 2018). "Measurement of serum IGF-1 is more practical and accessible, and pituitary tumour patients with hypopituitarism and low serum IGF-1 have been shown to have a high probability of GHD." (PMID 29609574, 2018). "Moreover, hypopituitarism and IGF-1 levels seem to be related to a worse cognitive performance, especially in the group of tests exploring the memory domain." (PMID 41853178, 2026). "At the time of conception, hypopituitarism was well compensated (sodium 140 mEq/L, potassium 4.1 mEq/l; insulin-like growth factor 1 (IGF-1) 160.3 ng/mL, normal range 107.8–246.7 ng/mL; fT4 11.7 pg/mL, normal range 9.2–16.8 pg/mL; fT3 3.8 pg/mL, normal range: 2-4.4 pg/mL)." (PMID 41359080, 2025). "The patients referenced in these studies did not exhibit abnormally low serum IGF-1 levels, which is indicative of hypopituitarism or growth-hormone deficiency." (PMID 40362202, 2025). "It is also worth briefly discussing our observation that IGF-1 level was negatively associated with non-treated hypopituitarism." (PMID 39997750, 2025). "In the multivariate logistic regression analysis the only determinant negatively associated with non-treated hypopituitarism was IGF-1 concentration." (PMID 39997750, 2025). "Given that TBI-induced hypopituitarism is relatively common (affecting up to 66% of TBI survivors), we hypothesized that IGF-1 deficiency might underlie the observed NVC impairments." (PMID 40360822, 2025). "Among hypopituitary patients with central hypothyroidism (n = 90), only IGF-1 concentration was negatively associated with non-treated hypopituitarism." (PMID 39997750, 2025). "When all hospitalization time points (n = 124) were considered, two determinants, i.e. ACTH and IGF-1 concentrations, were negatively associated with non-treated hypopituitarism in the univariate regression analysis." (PMID 39997750, 2025). "Additionally, a low insulin-growth factor 1 (IGF1), in the setting of severe stunting led to further evaluation of the full endocrine axis for hypopituitarism." (PMID 37386483, 2023). "A study investigating patients with multiple pituitary hormone deficiencies identified an independent effect of PRL on IGF-1 status through multiple regression analysis, though no direct correlation was found between actual PRL levels and IGF-1 levels in panhypopituitarism." (PMID 40370773, 2025). "Alleviating tumor compression on the pituitary gland and stalk, removing mammosomatotroph or mixed somatotroph-lactotroph tumors, and lowering GH and IGF-1 levels after surgery may be possible mechanisms that result in the recovery of hypopituitarism and hyperprolactinemia." (PMID 35154007, 2021). "Two patients (1 male with OSAS, 1 female without OSAS) had a deterioration of sleep parameters between T1 and T2 without changes in IGF-1 levels, presence of pituitary hormonal deficiencies, and with a similar BMI in 1 patient and a lower BMI in the other patient." (PMID 31612224, 2020). "Routine basal hormonal screening for TBI-induced hypopituitarism should include serum cortisol, free T3, free T4, TSH, IGF-1, FSH, LH, testosterone (in boys) or estradiol (in girls), prolactin, urine specific gravity, sodium, and plasma osmolality." (PMID 41300601, 2025). "Further studies, however, showed that age, the time of onset of GHD, and the degree of hypopituitarism, all had a significant influence on serum IGF-1 levels—sometimes expressed as standard deviation scores (IGF-1 SDS) or Z scores." (PMID 22899919, 2012). "Laboratory measurements were not indicative for pituitary insufficiency or GH insensitivity, however, IGF1 was low." (PMID 22693602, 2012).
hypopituitarism (continued). "Usually, low IGF-1 levels are the first sign of hypopituitarism, but normal levels should not exclude the presence of dysfunctions in other axes, particularly in patients with empty sella, for which the patterns of hormonal dysfunctions, if any, remains to be characterized." (PMID 32943019, 2020). "We show that a combination of GH and IGF-1 replacement therapy to increase both IGF-1 and IGF-BP3 plasma levels may indeed be an important novel therapeutic modality to treat AGHD independent of targeting anterior pituitary hormone deficiencies." (PMID 20843352, 2010). "Consistently, children with pan-hypopituitarism are not SGA and have no growth failure in the first months of life but frequently are hypoglycemic with low IGF1 levels." (PMID 34447729, 2021).
type 1 diabetes (80 papers, 2005 to 2026). "A longitudinal study in children and adolescents with Type 1 diabetes demonstrated similar findings, showing that low mean IGF-1 levels were independently associated with the progression of DR." (PMID 40362202, 2025). "The reduced production of IGF-1 in type 1 diabetes likely plays a pathogenic role in diabetic cardiomyopathy and strongly suggests that the cardioprotective effects of B12 is due partly to the restoration of IGF-1 levels." (PMID 34163008, 2021). "Dysregulation in the IGF-1 system in type 1 diabetes is associated not only with pure metabolic control but also with the development of severe complications such as end-stage renal disease and diabetes enteropathy." (PMID 29744370, 2018). "Similarly, the positive association between IGF1 and the fasting C-peptide/glucose ratio follows reported positive correlations of C-peptide and IGF1 levels in AAb+ individuals and in those with type 1 diabetes." (PMID 37537394, 2023). "We do not have data for IGF-1 in the T1DI cohort in order to evaluate whether there were any associations between IGF-1 levels and the risk of islet autoimmunity or type 1 diabetes." (PMID 35244713, 2022). "In type 1 diabetes, circulating IGF1 levels are negatively associated with glycemic control." (PMID 23781301, 2012). "We tested whether IGF1 levels are associated with occurrence of severe hypoglycemic events in patients with type 1 diabetes and whether the IGF1 concentration is influenced by glycemic control." (PMID 23781301, 2012). "Furthermore, it confirms that circulating IGF1 concentrations are low and negatively associated with glycemic control as indicated by HbA1c in type 1 diabetes." (PMID 23781301, 2012). "BAT transplantation has been shown to protect against both type 1 diabetes by improving glycemia with increased IGF-1 and type 2 diabetes by improving glucose tolerance with increased IL-6 or adiponectin." (PMID 39119146, 2024). "Microglial IGF-1 levels were reduced in type 1 diabetic mice (T1DM) mice, and the activation of spinal IGF-1 signaling maintained microglial IGF-1 expression in the spinal cord of diabetic mice and reduced neuro-inflammation." (PMID 39135776, 2024). "The importance of IGF-1 as a batokine was highlighted in a study involving BAT transplantation in mice with type 1 diabetes, which showed a notable and swift rise in IGF-1 expression within the BAT, coupled with increased levels of circulating IGF-1." (PMID 39335642, 2024). "As noted in the literature when selecting these targets, reduced levels of IGF1 have been reported in children, adolescents and adults who are autoantibody positive (AAb+) or who have type 1 diabetes." (PMID 37537394, 2023). "In patients with type 1 diabetes, lower 25(OH)D3 was significantly correlated to lower apolipoprotein-A1 and IGF-1 Z-score, and higher ALAT activity, GFR, and plasma glucose." (PMID 38084202, 2023). "Another condition is hepatic resistance in children affected by poor-controlled type 1 diabetes (T1D), which is treated with insulin, resulting in the decrease of IGF-1 levels." (PMID 37008935, 2023). "One important RCT showed that most people with type 1 diabetes have low levels of circulating IGF-1." (PMID 37513978, 2023). "Previous work showed that CM (plus honey) consumption decreased circulating glucose, increased insulin concentrations, and increased IGF-1 concentrations in type 1 diabetic rats." (PMID 35804599, 2022). "There was a significant interaction between group and time on IGF‐1 isoform expression, showing that all IGF‐1 mRNA variants increased after training only in type 1 diabetes." (PMID 34995365, 2022). "Taken together, our results indicate that IGF-1 signaling and superoxide scavenging, both partially but additively mediate the cardioprotective effects of B12 in type 1 diabetes." (PMID 34163008, 2021).
type 1 diabetes (continued). "The exact mechanisms by which type 1 diabetes (T1D) and poor glycemic control relate to the GH-axis and its interaction with IGF-1 and IGFBP-3 remain to be determined." (PMID 33905470, 2020). "When BAT was placed in mice with type 1 diabetes, a significant and sharp increase in the expression of IGF-1 in BAT and circulating IGF-1 levels together with mitigated pro-inflammation and ameliorated glucose homeostasis was observed." (PMID 31208019, 2019). "Previous Type 1 diabetes studies on rats and humans showed lower plasma IGF-1 levels, consistent with findings in the present study." (PMID 30297647, 2018). "IGF1 levels were generally lower in our population of patients with type 1 diabetes than previously reported for healthy subjects." (PMID 23781301, 2012). "Raised IGF1 levels have been proposed as a mechanism, but bioavailable IGF1 is decreased in type I diabetes." (PMID 15886700, 2005). "Severity of DR in patients with type 1 diabetes is negatively correlated with serum IGF-1 levels." (PMID 37358957, 2023). "IGF-1 activation of AMP-activated protein kinase (AMPK) in DRG sensory neurons may contribute to protection against neurodegeneration in type 1 diabetes." (PMID 35298717, 2022). "To date, the clinical relevance of TBS analysis was verified in several endocrinopathies associated with increased fracture risk, including disorders of the growth hormone/insulin-like growth factor 1 (GH/IGF-I) axis, diabetes type 1 and 2, primary hyperparathyroidism, and thyroid diseases." (PMID 33584537, 2020). "Impaired GH/IGF-1 axis and decreased bone turnover during the period of skeletal growth in adolescents with type 1 diabetes may attenuate formation during this period of bone growth." (PMID 30250851, 2018). "In conclusion, our results show that in newly diagnosed adolescents with type 1 diabetes and deranged metabolism, IGF-1 levels are low and rapidly improving with insulin treatment but later tend to decrease concomitantly with declining endogenous insulin secretion." (PMID 29744370, 2018). "A similar IGF-1 peak is also seen in adolescent with type 1 diabetes, but the peak is lower and may be delayed in girls." (PMID 29744370, 2018). "In conclusion, our results show that in newly diagnosed adolescents with type 1 diabetes and deranged metabolism, the IGF-1 level is low and rapidly improves with insulin treatment but later tends to decrease concomitantly with declining endogenous insulin secretion." (PMID 29744370, 2018). "Furthermore, elevated protein levels of IGFBP5 and reduced protein levels of IGF1 are found in young patients with type I diabetes showing decreased bone mass." (PMID 26025657, 2015). "IGF1 is implicated in both muscle and bone turnover as well as lipid metabolism and growth, and our study supports that a low IGF1 level in patients with type 1 diabetes may increase by lowering HbA1c and thereby diminish the negative influence of a low IGF1 on the body." (PMID 23781301, 2012). "Uric acid and insulin-like growth factor-1 (IGF-1) were lower, and sex hormone binding globulin (SHBG) was higher, in participants with type 1 diabetes." (PMID 41285865, 2025). "For example, IGF-1 peptide improved nerve regeneration in both normal and streptozotocin (STZ)-induced type 1 diabetic rats after sciatic nerve crush." (PMID 35298717, 2022). "For example, insulin-like growth factor-1 activates AMPK to augment mitochondrial function and correct neuronal metabolism in sensory neurons in type 1 diabetes." (PMID 33029194, 2020). "IGFs (IGF1 and IGF2) expedite glucose metabolism with their availability modulated by IGF binding proteins, and function as prognostic factors for type 1 diabetes." (PMID 32694937, 2020). "Previous studies have supported the existence of a negative association between IGF1 levels and HbA1c, and one study found that the IGF1 level in patients with type 1 diabetes is low but not correlated with HbA1c levels." (PMID 23781301, 2012).
type 1 diabetes (continued). "In addition, insulin-like growth factor 1 (IGF-1) was shown to be protective against type I diabetes in non-obese diabetic mice as shown by reduced β-cell apoptosis resulting from increased expression of the anti-apoptotic Bcl-xL and Bcl-2." (PMID 31552099, 2019).
endometrial cancer (79 papers, 2003 to 2025). Primary or metastatic malignant neoplasm involving the endometrium (mucous membrane that lines the endometrial cavity). "There is evidence for a direct effect on endometrial cancer cells of insulin and IGF-1; activation of the insulin receptor causes an increase in cell proliferation and inhibition of apoptosis through both the MAPK and PI3K/Akt pathways." (PMID 34359595, 2021). "On the basis of data generated by profiling of LS patients, our overall aim was to delineate IGF1-dependent metabolic pathways associated with endometrial cancer protection." (PMID 31320996, 2019). "Recent studies demonstrated that MK-0646 had a potent anti-proliferative effect in Type I and II endometrial cancer cell lines, associated with a decrease in IGF1-induced IGF1R, AKT, and ERK1/2 phosphorylation." (PMID 29922232, 2018). "Supporting our findings, other studies also reported that the level of IGF1 was associated with endometrial cancer as well as other cancer types." (PMID 27409342, 2016). "Another case–cohort study that included 250 incident endometrial cancer patients and 465 controls assessed the association between endometrial cancer risk and serum levels of IGF1, IGFBP3, insulin, and estradiol." (PMID 24904527, 2014). "In summary, more research is needed to firmly establish the diagnostic and prognostic value of circulating IGF1 in endometrial cancer." (PMID 24904527, 2014). "Low levels of free IGF1 and high insulin levels were associated with endometrial cancer risk after adjustments for age, hormone therapy use, and estradiol levels." (PMID 24904527, 2014). "However, intriguingly, our subgroup analysis reveals a positive association between both IGF1 and 2 and an increased risk of endometrial cancer within the obese BMI category, translating to a substantial 3.5 and 3.7-fold increase in cancer risk, respectively." (PMID 38339282, 2024). "IGF1 is one of the genes related to the insulin signaling pathway, and it’s up-regulation may cause polycystic ovary syndrome and endometrial cancer." (PMID 34054819, 2021). "However, the association between serum IGF1 levels and endometrial cancer risk, and the diagnostic or prognostic value of this correlation, is still an unsettled issue." (PMID 31320996, 2019). "Given that estradiol is the main risk factor for endometrial cancer, data are consistent with the notion that downstream activation of the IGF1-mediated pathway by mutation could play a major role in the progression to ER-independent tumors." (PMID 24904527, 2014). "This study supports CUDC-907 as a potent treatment strategy in endometrial cancer and identifies IGF-1 as a potential surrogate serum biomarker for therapeutic response." (PMID 41262902, 2025). "Endometrial cancer cells express insulin receptors and both insulin and IGF-1 display mitogenic and antiapoptotic activity, thus potentially contributing to progression of cancer." (PMID 37405618, 2023). "Insulin and IGF-1 are each able to induce the expression of EMT biomarkers in endometrial cancer cell lines." (PMID 36052252, 2022). "Several studies have revealed that an overexpression of receptor tyrosine kinase (IGF1R) which mediates actions of insulin-like growth factor 1 (IGF1) is related to endometrial cancer." (PMID 35264951, 2022). "In summary, OR5H2 emerged as a novel target for positive regulation by IGF1, with potential relevance in endometrial cancer." (PMID 34204736, 2021). "IGF1 signaling contributes to the regulation of EMT 35, and our result also indicated the potential function of IGF1 in the regulatory role of FTO in endometrial cancer." (PMID 34149936, 2021). "The aim of our study was to investigate the regulation of OR5H2 gene expression by IGF1 in endometrial cancer." (PMID 34204736, 2021).